FGFR2 (fibroblast growth factor receptor 2)
Diseases named in the same sentence as FGFR2 in open-access papers (continued):
Sharing a sentence is not in itself a finding about the gene and the disease.
tumor (continued). "AZD4547 is a potent, oral, highly selective inhibitor of FGFR1–3 with proven antitumour properties from preclinical studies, including work in FGFR2-amplified GC xenografts that demonstrated complete and prolonged tumour regression in several AZD4547-treated animals." (PMID 28070720, 2017). "NGS-based profiling of the tumor genome identified a single nonsynonymous mutation among the many genes noted for recurrent mutations in CRC (e.g., KRAS, NRAS, BRAF, PIK3CA) and a striking focal amplification of the FGFR2 gene." (PMID 28835367, 2017). "In addition, FGFR2 was shown to contribute to the maintenance of tumour-initiating cells (TICs), a subpopulation with increased tumourigenic potential, self-renewal, heterogeneous differentiation and bipotency." (PMID 27476168, 2016). "Given the significant relationship between FGFR2 IHC positivity and tumor depth, we hypothesized that FGFR2 expression accelerates tumor cell proliferation." (PMID 26933914, 2016). "However, only FGFR1 was expressed at high level, with a mean transcript expression of 187 RPKM in NRH-LS1 (and 143 in tumor B), compared to 0.3, 47, and 7.9 for FGFR2, FGFR3 and FGFR4, respectively." (PMID 27409346, 2016). "Interestingly, FGFR2 depletion appeared to induce a significant increase of Snail1 mRNA in HaCaT pBp-FGFR2b cells, suggesting that, consistent with its tumor suppressive role, FGFR2b would exert a repressive role on this master inductor of EMT." (PMID 26713601, 2016). "According to the cell cycle analysis at 72 h after FGFR2 knockdown by siRNAs, the FGFR2-overexpressing OACM5.1C tumor cells were significantly accumulated in the G0/G1 phase population (P < 0.05), and concomitantly decreased in the G2/M phase population (P < 0.05)." (PMID 26933914, 2016). "These authors proposed the exciting possibility that the phenotypic versatility of malignant tumor cells might directly derive from FGFR2 splicing decisions, which enable them to promptly respond to different microenvironmental signals." (PMID 26713601, 2016). "The recent identification of the driver role of FGFR2 fusions in iCCA, as well as other tumor types, provides a promising path forward in the selection of patients that may respond to FGFR inhibitors in a clinical setting." (PMID 27627808, 2016). "Although FGFR2 amplification was associated with FGFR2 IHC positivity, FGFR2 IHC positivity, but not FGFR2 amplification, strongly correlated with tumor aggressiveness, and patient outcome in this study." (PMID 26933914, 2016). "FGFR2 expression (but not FGFR2 amplification) was associated with tumor growth and patient outcomes." (PMID 26933914, 2016). "In EGJ adenocarcinoma, the FGF-FGFR2 signaling axis may be a crucial pathway in tumor progression; thus, this cancer may be adequately managed by an FGFR2-specific inhibitor." (PMID 26933914, 2016). "We attribute this discrepancy to the intra-tumor heterogeneity of FGFR2 expression." (PMID 26933914, 2016). "In conclusion, we found that (i) FGFR2 amplification is associated with FGFR2 expression, and (ii) FGFR2 expression, but not FGFR2 amplification, is associated with depth of tumor invasion and poorer outcomes in EGJ adenocarcinoma." (PMID 26933914, 2016). "Several FGFR tyrosine kinase inhibitors (TKIs) such as dovitinib, ponatinib, NVP-BGJ398 and AZD4547 have been able to inhibit growth of GC cell lines harboring FGFR2 amplification and shrink tumor xenograft using the same FGFR2 amplified cell lines implanted in nude mice." (PMID 25576915, 2015). "Vascular endothelial cells as well as the tumor cells were positive for FGFR2." (PMID 26036639, 2015). "However, it is currently not well understood how FGFR-2 signaling seems to exhibit tumor suppressing effects in some cells and oncogenic effects in others." (PMID 26465941, 2015). "Taken together, our data suggested that formononetin could function as a novel FGFR2 inhibitor that suppresses tumor angiogenesis and growth." (PMID 26575424, 2015).
tumor (continued). "In the tested cell lines, this FGFR inhibitor showed potent and selective anti-tumor activity against the cell line with known FGFR2 amplification (NCI-H716), compared with other cell lines with low/not detected protein expression of FGFR2 (Caco2, HCT116 and HCA7)." (PMID 26675289, 2015). "Dovitinib inhibited tumor growth in an FGFR2-amplified primary human GC xenograft model." (PMID 26000013, 2015). "For example, the index patient in this study may have conceivably responded to a FGFR2 inhibitor based on FGFR2 amplification in the primary tumor." (PMID 25315765, 2014). "Furthermore, overexpression of an SNV in ERRFI1 (E384X), a negative regulator of EGFR, was detected in a non-FGFR2 translocation patient's tumor." (PMID 24550739, 2014). "A further advantage of a KGFR-specific antibody is represented by the fact that both FGFR2 isoforms are expressed in normal tissue, whereas tumor samples expressed mainly KGFR, as previously reported by the literature and as also confirmed by our Real-Time PCR data." (PMID 24899248, 2014). "Moreover, we found human breast TICs enriched in a FGFR2+ population which was sufficient to initiate tumor growth." (PMID 23300950, 2013). "Our study provides further evidence for the implication of FGFR2 in tumor development." (PMID 23527311, 2013). "Moreover, human breast TICs isolated from patient tumor samples were found enriched in a FGFR2+ population that was sufficient to initiate tumor growth." (PMID 23300950, 2013). "Thus, FGFR2 plays important roles in CRC progression in correlation with tumor cell migration, invasion, and growth." (PMID 22701813, 2012). "FGF7 induced an increase of VEGF-A; thus, FGF-7 and its receptor FGFR2 IIIb may be involved in tumor angiogenesis in CRC." (PMID 22701813, 2012). "The role of FGFR2 in tumor development and progression appears to be more complex." (PMID 23185502, 2012). "Interestingly, a bi-genic mouse line that has repressed FGFR2 combined with high FGFR1 activity (resembling our shR2 cells) shows enhanced tumor development in the prostate when compared to either repression of FGFR2 or overexpression of FGFR1 alone." (PMID 23185502, 2012). "RSK4 is also associated with the FGFR2/RAS/ERK signal pathway and is a tumor suppressor." (PMID 22548175, 2012). "Since the percentage of stroma in the primary tumor may vary considerably and FGFR2 signaling in the stroma could influence cell proliferation, we explored whether patients with higher FGFR2 mRNA expression in fibroblasts had a higher stroma percentage." (PMID 21767389, 2011). "More notably, a proportion of tumours showed definite nuclear staining for FGFR2." (PMID 21418638, 2011). "A comparison of FGFR2 staining with oestrogen and progesterone receptor status of tumours." (PMID 21418638, 2011). "In addition, opposite effects of intron 2 SNP genotypes on FGFR2 mRNA expression have been reported in tumor tissue and normal breast tissue." (PMID 21767389, 2011). "A comparison of FGFR2 staining between tumour and adjacent normal tissue within the same slide." (PMID 21418638, 2011). "One mechanism for over-expression of FGFR2 would be increase in copy number of FGFR2 in tumours." (PMID 21418638, 2011). "We explored tumor parameters in patients with different FGFR2 mRNA levels in their fibroblasts." (PMID 21767389, 2011). "However, although FGFR2 signalling clearly plays an oncogenic role in some cancers, in several tissues, including bladder, skin and prostate, it also can act as a tumour suppressor." (PMID 19410332, 2009). "Moreover, patients with high FGFR2 expression had significantly more nodal invasion, a larger tumour size, and a worse UICC Stage (P=0.0263, P=0.0469, and P=0.022, respectively, by χ2-test)." (PMID 18594526, 2008).
tumor (continued). "Of these, 25 have a mutation frequency above 5% in one or more tumour type while the other three, ERBB2, FGFR2 and SUFU, have biologically plausible mutations but a low mutation frequency (mutation frequencies in all available data are; 1.2% for ERBB2, 2% for FGFR2 and 1.6% for SUFU)." (PMID 16421597, 2006). "A further detailed characterisation revealed specific targetable genetic alterations, such as ELF3 mutations and FGFR2 gene fusions, with variations in mutation types and frequencies across BTC subtypes suggesting a role for immunomodulatory treatments in hypermutated tumours." (PMID 40093398, 2025). "Our findings extend this knowledge by demonstrating that FGFR2 expression is positively correlated with markers of an immunosuppressive TIME, namely CD163+ macrophages and FOXP3+ regulatory T cells, and that these associations are particularly evident in luminal A tumours." (PMID 41018083, 2025). "It was indicated that FGFR2 gene abnormalities may be caused by factors within the tumor without external factors and old ages." (PMID 41226813, 2025). "The CTNNB1-mutant (p.I35T) tumor in our series was morphologically distinct, displaying more fibrous stroma, focal glandular differentiation, less primitive cytologic features, a lower mitotic rate, and a lower Ki-67 proliferative index compared to the FGFR2-mutant tumors." (PMID 40906279, 2025). "In addition, genes that are characteristic of CCA, such as the IDH and FGFR2 genes, could also be investigated as part of a molecular tumor workup." (PMID 40227700, 2025). "Moreover, contemporary investigations have demonstrated that novel structural changes in FGFR2 and FGFR3 are frequently linked to an aggressive tumor biology and specific gene expression signatures, thus validating their function as powerful, clinically actionable drivers." (PMID 41567627, 2025). "Thus, the so-called cytotoxic drug selectively targets tumor cells with FGFR2 overexpression." (PMID 39156005, 2024). "Notably, although sample sizes were small, dual FGFR2b/c expressing GCs had a significantly poorer outcome compared to GCs that only overexpressed FGFR2b, which may be due to the expanded repertoire of FGFs capable of activating FGFR2 in these tumours." (PMID 38791079, 2024). "Thus, the potential functions of FGFR2 within the tumor mass remain unclear and need further investigation." (PMID 37579831, 2023). "Interestingly, FGFR2 has been shown to be druggable in other tumour entities." (PMID 37543577, 2023). "Similarly, FGFR2 which promotes tumor stemness, could be targeted to block the FGF7 expressed from CAFs81." (PMID 37633924, 2023). "Similarly, our findings also marked the presence of FGFR2 deletions across multiple tumor types." (PMID 37964396, 2023). "Interestingly, 17.2% of the patients with stage II/III/IV tumours had FGFR2 mutation while no FGFR2 mutation was found in the stage I group (p < .05)." (PMID 37272300, 2023). "While FGFR2-amplified tumor cells accounted for 10–20% of cells in 3/4 primary tumors and were mainly found in the central tumor area, up to 90% of the infiltrating tumor cells counted were evenly distributed in the center and periphery in 1/4 primary tumors (75% intratumoral heterogeneity)." (PMID 36416959, 2023). "Our findings that EC‐linked mutations in FGFR2 increase ADAM17 activity provides a well‐defined description of a molecular mechanism associated with these pathogenic mutations, implicates increased ADAM17 activity in tumour formation and identifies a new druggable target in EC." (PMID 37165578, 2023). "Moreover, the data showed, in patients with ER+PR+ but not ER+PR− tumours, a positive association between FGFR2 and good prognosis." (PMID 35726195, 2022). "Based on our results and others, FGFR2 IHC using FGFR2 antibody may not be a useful diagnostic utility to identify cancer patients with FGFR2 aberration in their tumor specimen." (PMID 35342406, 2022).
tumor (continued). "However, in tumor-bearing mice, they were accumulated in tumor regions, demonstrating that FGFR2+ fibrocytes could be recruited into tumor mass in vivo." (PMID 35941662, 2022). "Sanger sequencing on tumor samples after progression confirmed FGFR2-CLIP1 fusion in all samples, furthermore, whole-exome sequencing revealed 242 unique mutations to post progression and a FGFR2 kinase domain acquired mutation, FGFR2 N549H in a single liver tumor." (PMID 35444941, 2022). "Interestingly, all 5 CBD cancer patients with FGFR2 fusion had PD-L1 positive tumor." (PMID 35342406, 2022). "Furthermore, IHC revealed that RK-019 could prevent FGFR2 phosphorylation, induce apoptosis, and inhibit cell proliferation in the tumor sections." (PMID 36210834, 2022). "We performed DNA methylation analysis of the encoding genes FGFR1, FGFR2, FGFR3, FGFR4, FGF1-14, FGF16-23, and CCND1 at single CpG site resolution (840 CpG sites) employing The Cancer Genome Research Atlas (TCGA) HNSCC cohort comprising N = 530 tumor tissue and N = 50 normal adjacent tissue samples." (PMID 34933671, 2021). "Specifically, these mutations are located on five tumor suppressors (SDHA, RB1CC1, PTCH1, DMBT1, BCR) and eight proto-oncogenes (MERTK, CSF1R, MYB, ROS1, PCM1, FGFR2, MYH11, BRCC3) and have an allele frequency lower than 0.01 in the Genome Aggregation Database (GnomAD)." (PMID 33466296, 2021). "Putative oncogenic and targetable mutations could be found in individual tumor samples in FGFR2 (SNUC, SNSCC non-keratinizing), FGFR3 (SNSCC-associated with ISP), MAP1K2 (SNAC), MET (ISP-associated SNSCC), MAP2K1 (SNAC) and HRAS (SNSCC keratinizing and ITAC)." (PMID 34885191, 2021). "Furthermore, to the best of our knowledge, the mutation in the FGFR2 juxtamembrane region of patient 2 has not yet been reported in any tumor, nor have FGFR downstream activation and response to FGFR inhibition been analyzed so far." (PMID 34480077, 2021). "The total number of tumor samples from individual cancer types varied from 36 (CHOL) to 1,084 (BRCA), and those with too few tumor samples might not represent the complete picture of FGFR2 mutation status." (PMID 33968743, 2021). "Furthermore, the frequency of FGFR2 alteration across all tumor types was between 0 and 20%, and this low alteration frequency could make our analysis challenging." (PMID 33968743, 2021). "On the other hand, we detect female-biased genes that may contribute to HCC aggressiveness in females: overexpression of FGFR2 has been associated with advanced clinical stages, and NTS is known to induce local inflammation and to promote tumor invasion in HCC." (PMID 31615477, 2019). "However, keratinocyte-specific deletion of the FGFR2 gene made mice more sensitive to chemical carcinogenesis, suggesting that FGFR2 may function as a tumor suppressor." (PMID 31619201, 2019). "The data presented here suggests that while Vegfr2 heterozygosity strikingly leads to defects in tumor growth and tumor angiogenesis in all the three tumor models, additional loss of endothelial Fgfr1 and Fgfr2 displays no further effects on tumor growth and tumor angiogenesis." (PMID 30283071, 2018). "Notably, the patient failed on three prior regimens before enrollment into the LY2874455 (pan-FGFR inhibitor) trial, wherein the patient, whose tumor was characterized as exhibiting FGFR2 protein overexpression by IHC as well as high-copy-number FGFR2 amplification, responded for over 1 year." (PMID 28122360, 2017). "Moreover, FGFR2 expression may be a better biomarker of tumor aggressiveness in EGJ adenocarcinoma than FGFR2 amplification." (PMID 26933914, 2016).
tumor (continued). "Additionally, we assessed the anti-tumor activity of ARQ 092 in in vivo mouse models implanted with AN3CA cells (mutant PIK3R1, PTEN deficient, and activating mutation of FGFR2), KPL-4 cells (over-expression of HER2 and mutation in PIK3CA); and ZR-75-1 cells (ER positive, PTEN deficient)." (PMID 26469692, 2015). "Off target efficacy resulting from inhibition of angiogenic kinases in addition to FGFR2 inhibition could explain the anti-tumor activity exhibited in patient 6, as pazopanib has been shown to have nanomolar range potency towards VEGFR1-3, PDGFRA/B and CKIT as well." (PMID 24550739, 2014). "The association between tumour nuclear FGFR2 expression and expression in the original normal tissue is interesting, as it suggests that the level of FGFR2 expression may be programmed into the normal tissue in advance of the cancer developing." (PMID 21418638, 2011). "Ki23057 might decrease the growth of DGC tumour by inhibiting the FGFR-2 signalling pathway." (PMID 19738610, 2009). "Using Smart-seq2, investigators further identified ESRP1/2 as critical regulators of FGFR2 splicing during EMT, thereby providing mechanistic insight into how splicing contributes to tumor plasticity." (PMID 41584352, 2026). "This combined therapy works by inhibiting the FGFR2/3 and FGF19/FGFR4 signaling pathways, thereby curbing tumor cell proliferation and inducing apoptosis." (PMID 41328353, 2026). "The resultant shift in the FGFR2 IIIb/IIIc ratio contributes to EMT signaling, enhancing tumor cell invasion and metastasis." (PMID 41584352, 2026). "Fibroblast growth factor receptor 2 (FGFR2) plays a vital role in lung morphogenesis and contributes to the tumor angiogenesis in most NSCLCs10." (PMID 40057671, 2025). "Our genomic analysis showed copy number disruption of FGFR1/2 across the cell lines; a result reflected in our human UPS tumour datasets where FGFR1 was CN altered in 60% of cases and FGFR2 in 50%." (PMID 40415599, 2025). "Mechanistically, ΔNp63α transcriptionally activates pro-survival genes (e.g., FGFR2, EGFR), and represses tumor suppressors (e.g., p73, p21)." (PMID 40223122, 2025). "While the observed correlations between FGFR2 and CD163+ or FOXP3+ immune cells are modest, their selective presence in ER+ tumours is noteworthy and warrants further investigation." (PMID 41018083, 2025). "Targeted drugs, such as FGFR2 inhibitors and IDH1 inhibitors, block tumour cell proliferation and signalling pathways, thus increasing the effectiveness of immunotherapy and restoring the ability of the immune system to recognize tumours." (PMID 40861435, 2025). "Taken together, although the study is limited to a relatively small cohort, the findings suggest that FGFR2 expression may be associated with features of an immunosuppressive TIME in luminal BCa, and could serve as a potential biomarker for identifying this tumour microenvironment subtype." (PMID 41018083, 2025). "Patients with FGFR2-positive circulating tumor cells (CTCs) had significantly worse recurrence-free survival, and there was correlation between CTC and primary tumor FGFR2 expression." (PMID 41303727, 2025). "Molecular testing of the tumor tissue at diagnosis revealed ERBB2 gene amplification (estimated copy number of 6) and concurrent FGFR2 amplification (estimated copy number of 128)." (PMID 41357601, 2025). "The role of FGFR2 and HIF1A signaling was further validated in subcutaneous xenograft and orthotopic tumor metastasis models." (PMID 40225580, 2025).